IL17A (interleukin 17A)
Diseases named in the same sentence as IL17A in open-access papers (continued):
Sharing a sentence is not in itself a finding about the gene and the disease.
Arthritis (continued). "Of note, we also observed a marked increase in IFN-γ production in mice exposed to PM2.5; IFN-γ suppresses Th17 differentiation and IL-17A production in experimental models of arthritis and autoimmune encephalomyelitis." (PMID 36477357, 2022). "Of note, serum concentrations of IL-6 and IL-17A were higher in the combined ICI arthritis group than in the PD-1 inhibitor arthritis group, but the differences were not statistically significant." (PMID 35413951, 2022). "In the AA model, treatment with anti-IL-17A completely alleviated arthritis, lowered the level of RANKL, and inhibited structural damage to the bones." (PMID 36296709, 2022). "The results showed that GMSC‐Exo have the same or even more immunoregulatory effects compared with GMSC in some aspects, such as promoting the secretion of IL‐10, inhibiting that of IL‐17A, and reducing the incidence of arthritis and bone erosion." (PMID 34953015, 2022). "Several animal models have studied the role of IL-17A and its receptors in (inflammatory) arthritis; injection of IL-17A induced the manifestations of OA in a rabbit model." (PMID 34054865, 2021). "Because IL-23 induces TNF expression and TNF transgenic mice developed chronic arthritis, these investigators attempted to identify the mechanism for IL-23-induced arthritis with regards to IL-17A, TNF, and CD4+ T cells." (PMID 34067675, 2021). "Blocking IL-17A or TNF along with the depletion of CD4+ T cells produced protective effects against the development of arthritis with modulation of TRAP5b." (PMID 34067675, 2021). "Pro-inflammatory cytokines such as IL-1 beta and IL-17A contribute to arthritis pathogenesis and trigger joint inflammation." (PMID 34925335, 2021). "Th17 cells are characterized by the production of IL-17A, which induces arthritis progression and the production of RANKL, leading to osteoclast formation." (PMID 34067675, 2021). "We previously demonstrated that selective blockade of IL-17A significantly reduces spondylitis and arthritis development in the inducible HLA-B27 tg rat model of SpA." (PMID 34552583, 2021). "The significantly higher incidence observed in the group that received EBV DNA 6 days prior to collagen is hence likely the result of an EBV DNA-triggered IL-17A response early in the arthritis-induction protocol." (PMID 34040613, 2021). "We show decreased prevalence of arthritis in p110α−/−ΔT mice, with decreased IL-6 and IL-17A secretion and enhanced anti-CII IgG1 antibodies in response to CII." (PMID 34203838, 2021). "Collinsella has previously been shown to influence production of thepro-inflammatory cytokine IL-17A; its role in altering gut permeability and diseaseseverity was confirmed in experimental arthritis." (PMID 34485761, 2021). "In the same accelerated HLA-B27tg rat model, prophylactic anti-IL-17A treatment significantly delayed the development and decreased the severity of spondylitis and arthritis." (PMID 34267743, 2021). "Another major proinflammatory cytokine playing a role in the pathogenesis of arthritis is interleukin 17A (IL-17A)." (PMID 34502384, 2021). "Consistent with the observed clinical and histopathological arthritis phenotype, we found increased expression levels of Tnf, Il1b and the IL-23 target genes Il17a and Il22 in the joints of IL-23 EEV injected mice." (PMID 33983951, 2021). "In a type II collagen-induced arthritis rat model, MT exerted its anti-arthritis effects via down-regulation of pro-inflammatory cytokines and proteins (IL-6, IL-8, IL-1β, IL-17A, and TNF-α) and down-regulation of NF-κB." (PMID 33041782, 2020). "Arthritis progression and joint damage were significantly milder in IL‐23R−/− mice, which revealed less IL‐17A+ cells in their lymphoid tissues." (PMID 31778214, 2020). "AHR activation links the expansion of Th17 cells and the production of IL-17A, which is a pro-inflammatory cytokine that aggravates arthritis." (PMID 32218599, 2020).
Arthritis (continued). "The primary cytokines required for inducing arthritis in autoimmune models are IL-1β, IL-6, IL-17A, TNF, GM-CSF, and RANKL." (PMID 32792961, 2020). "In the progression of CIA, the local injection of IL-17A in knee-joint promotes arthritis and exacerbates joint damage." (PMID 33613566, 2020). "In a zymosan-induced model of interstitial lung disease associated with arthritis development, GM-CSF blockade in SKG mice prevented and ameliorated lung and joint inflammation, while IL-17A blockade had only a minor effect on disease severity." (PMID 31919358, 2020). "After treated with enrofloxacin, significant alteration in cytokine expressions were detected, including higher levels of IFN-γ and IL-17A in arthritis model mice and higher TNF-α, IL-1β levels in chicken models." (PMID 31069173, 2019). "These suggest that further applications, which suppress inflammatory enhancers, especially IL-17A, should be considered as a target for arthritis research and therapy." (PMID 31614911, 2019). "Although dual blockade of TNF-α and IL-1β, or IL-1β and IL-17A reduces murine arthritis, spontaneous skin infections were observed." (PMID 30626891, 2019). "In the HLA-B27 transgenic rat model of SpA, rapamycin inhibits arthritis and spondylitis development and severity, reduces articular bone erosions, decreases pathologic new bone formation and suppresses IL-17A expression." (PMID 32194539, 2019). "For instance, in the context of arthritis, IL-17A is able to induce IL-6 production by synoviocytes in synergy with the other proinflammatory cytokines such as IL-1 or TNF-alpha." (PMID 31485194, 2019). "It is noteworthy that IL-17 and Th17 play a role in early stages of CIA in mice, and that anti-IL17A antibodies can help control arthritis in CIA mice." (PMID 31533744, 2019). "In the HLA-B27 transgenic rat model of SpA, mTOR blockade reduces arthritis and spondylitis development and severity with decreased inflammation and bone defects with suppression of IL-17A." (PMID 32194539, 2019). "CCR6+ ILC3s from mice with arthritis expressed significantly higher levels of IL-17A and IL-22 mRNA than did comparable cells from control mice (p < 0.0001 and p = 0.015)." (PMID 31470891, 2019). "On the other side, blocking of endogenous IL-17A in the CIA model results in suppression of arthritis and reduction of joint damage." (PMID 31485194, 2019). "We confirmed previous data with early involvement of TNF followed by IL-17A and IL-23 before arthritis onset followed by IL-627." (PMID 29472591, 2018). "The first report of the involvement of IL-17A in arthritis was described in 1998 with the detection of IL-17A in synovial tissues from patients with RA." (PMID 29740348, 2018). "The IL-17 family includes six members, namely IL-17A, B, C, D, E and F. Of them, IL-17A is the principal effector of the IL-17-related inflammatory activity in Ps and arthritis." (PMID 29425183, 2018). "We have previously shown that treatment with anti-IL17A in both emerging and established disease resulted in decreased spondylitis and arthritis in the HLA-B27 tg rat." (PMID 30038617, 2018). "First, greater levels of IL-12/23p40, IFN-γand IL-17A were confirmed in supernatants of lipopolysaccharide (LPS)-stimulated TNFRp55-/-splenocytes obtained on arthritis onset (day 14 after Ye infection)." (PMID 29494692, 2018). "After arthritis onset, IL-17A was strongly upregulated, suggesting an adaptative response after its innate response in prearthritis phase." (PMID 29472591, 2018). "We also observed reductions in TNF-α, IL-17A, IL-1β expression and bone destruction even when transfer occurred after the onset of arthritis." (PMID 29535721, 2018). "For instance, bispecific monoclonal antibodies recognising IL-17A and IL-1β have been recently tested by Li and colleagues and showed to be effective to ameliorate the outcome of animal models of arthritis while human studies are underway." (PMID 29425183, 2018).
Arthritis (continued). "The inhibitor showed good in vivo efficacy in an antigen-induced arthritis model in rats and reduced the frequencies of IL-17A producing cells in ex vivo recall assays." (PMID 29155882, 2017). "As pro- or anti-inflammation cytokines are often related to the pathology of arthritis, we also examined the secretion levels of IL-1β, IL-6, IL-17A, TNF-α and IL-10 in AA models." (PMID 28352114, 2017). "A significant correlation was observed between IL-6, IL-17A as well as IL-1β hind paw gene expression levels and the corresponding hind paws arthritis score, and ankle diameter." (PMID 28759646, 2017). "Pristane-primed, which resulted in the most severe arthritis in the recipient rats, measured with AUC (area under the curve), exhibited the highest IL-17A gene expression." (PMID 29118363, 2017). "The RORγt inhibitor was able to attenuate the knee swelling response in an antigen-induced arthritis (AiA) model performed in rats and inhibited IL-17A cytokine production in ex vivo recall assays." (PMID 29155882, 2017). "IL-17A released by Th17 cells can promote CIA arthritis, and the inhibition of IL-17A can reduce arthritis." (PMID 28562338, 2017). "Later, it was found that mice deficient in IL-17 receptor subunit A were protected from the serum-induced arthritis, while recently, it was further demonstrated that IL-17A KO mice exhibited reduced arthritis." (PMID 27313578, 2016). "IL-17A promotes joint inflammation, cartilage degradation and bone erosion, which is consistent with data from experimental models of arthritis." (PMID 27169372, 2016). "In collagen-induced arthritis, clinical scores and serum concentrations of interleukin (IL)-17A were significantly decreased in T-Red mice." (PMID 26081938, 2015). "The objective was to determine the variability in expression of IL-17A, IL-17F and their receptors IL-17RA and IL-17RC in the synovia of patients with arthritis." (PMID 25146432, 2014). "It was found that in vivo neutralization of IFNγ exacerbates Th17 induced arthritis, and anti-IL-17A treatment delays onset of arthritis induction by Th17 cells." (PMID 25152827, 2014). "The expression of IL-17A is increased in inflammatory arthritis, and neutralization of IL-17A has been shown to reduce the severity of arthritis in the CIA model of RA." (PMID 25561237, 2014). "Significant numbers of DETs were highlighted in three key pathways: IL-17 Signaling [3 genes; p = 3.1×10−4], Il-17A Signaling in Gastric Cells [2 genes; p = 9.6×10−4] and Role of IL-17A in Arthritis [2 genes; p = 4.4×10−3]." (PMID 23520485, 2013). "Conversely, inhibition of IL17 by antibodies against IL-17A or its receptor IL17RA protected against the development of arthritis." (PMID 23956763, 2013). "Persistent blocking of IL-23 activity before inducing the AIA flare-up significantly prevented the expression of severe joint inflammation with lower synovial mRNA expression of IL-17A and IL-22." (PMID 23469022, 2013). "Polymerized-Type I Collagen and methotrexate/Polymerized Collagen treatments had a sustained effect in early and established arthritis model until the second sacrifice (follow up) on the percentage of IL-17A-producing CD4+ T." (PMID 22028728, 2012). "To confirm a role of IL-17 in the pathogenesis of CCR2-mediated exacerbation of arthritis, we examined the effect of a murine anti-IL-17A antibody on the development of CIA in CCR2−/− mice." (PMID 21991368, 2011). "This suggests that IL-17A is particularly involved in the initiation phase of arthritis, generally characterized by the generation of an autoimmune response." (PMID 22028860, 2011). "The notion that IL-17RA amplifies of arthritis is further supported by the observation that overexpression of IL-17A aggravates serum-induced arthritis." (PMID 22028860, 2011). "We next examined the effect of TSA on IL-17A production, because IL-17 plays a central role in the induction of severe arthritis in SKG mice." (PMID 21592365, 2011).
Arthritis (continued). "In the collagen-induced arthritis model, IL-17A-/- mice are protected from joint disease with less TRAP+ cells correlating with reduced bone resorption, suggesting that IL-17A plays a role in osteoclastogenesis." (PMID 20167120, 2010). "Multiple animal models have demonstrated key roles of IL-17A (henceforth called IL-17) and Th17 cells in the immunopathology and joint damage of arthritis." (PMID 20824142, 2010). "Because the arthritis progression was IL-23 dependent, we further examined the role of IL-23 on the formation of IL-17A and IFN-γ-producing CD4+ T cells in this process." (PMID 20017902, 2009). "IL-17A was strongly dependent on TNF-α in the early stages of experimental arthritis; however, at a later stage the disease became IL-17A driven and both TNF-α and IL-1 independent." (PMID 19627579, 2009). "Inhibiting IL-17A release by blocking Th17 activation can reduce arthritis." (PMID 40128226, 2025). "We discovered that triptolide was successful in lowering IL-6, IL-17A, and arthritis scores." (PMID 40918529, 2025). "Furthermore, exosomes (exos) derived from human gingival MSCs (GMSCs) exhibited comparable or enhanced efficacy compared with GMSCs in suppressing IL‐17A and enhancing IL‐10 production, thereby reducing the incidence of arthritis and bone erosion." (PMID 38712483, 2024). "In the CIA model, the dual blockade of TNF and IL-17 gave better results than either monotherapy and in the TNFα transgenic animal model of arthritis, as well as cartilage and bone damage, were better controlled with bi-specific antibodies (anti-TNFα and anti–IL-17A) than with monotherapies." (PMID 37035302, 2023). "However, arthritis score and joint thickness tend to relieve from 40 days to 44 days since MT injection in IL17A vaccine group compared with KLH control group." (PMID 36737108, 2023). "Recently, immunization with the protein 14-3-3zeta (ζ), which is involved in T-cell polarization and IL-17A signal transduction, has been shown to suppress arthritis in 14-3-3ζ knockout inflammatory arthritis rat models by the suppression of IL-1α levels and amplified collagen production." (PMID 37893571, 2023). "Local IL-1 beta and IL-17A strongly contribute to progression of experimental and human arthritis." (PMID 35874732, 2022). "Only a low dose of xylitol given after inducing CIA could significantly upregulate the levels of anti-COII IgG, IL-6, IL-17A, and arthritis score." (PMID 34852827, 2021). "Male B6 mice injected with IL-23 EEV did not develop arthritis despite comparable serum IL-23 and IL-17A levels, degree of weight loss, and osteopenia with B10.RIII mice." (PMID 33983951, 2021). "Inflammation in the joint was associated with high levels of IL-17 producing γδ T cells, and the expression of retinoic acid receptor related orphan receptor gamma (RORγ)t was dependent upon IL-23 suggesting that IL-23 regulates IL-17A and RORγt expression in γδ T cells in arthritis." (PMID 32085540, 2020). "Evaluation of immune cells in lymphoid organs showed that injection of SR-A protein caused elevation of IL-17A in the serum associated with increased frequency of IL-17A-producing CD4+ T cells, implicating a linkage of the sSR-A activity with a pathogenic Th17 response in arthritis." (PMID 32312978, 2020). "Application of sCD83 not only reduced the clinical symptoms of arthritis, but also inhibited the antigen-specific T cell proliferation upon mBSA-restimulation and impaired production of key inflammatory effectors, including IL-17A, TNFα, IFNγ, and IL-6." (PMID 31001257, 2019). "On the other hand, IL-17A overexpression by a minicircle DNA led to a bone phenotype with periarticular bone loss mimicking an erosive inflammatory arthritis without arthritis evidence." (PMID 31485194, 2019). "Cell transfer of CD4+ T cells from Il17a−/− SKG mice into T cell-deficient mice completely failed to induce arthritis." (PMID 31497022, 2019).
Arthritis (continued). "Although IL-17A and IL-17F have been reported to be associated with collagen-induced arthritis, and arthritis in experimental animal models, there is no study about relationship between rs2275913 (IL-17A SNP) and rs763780 (IL-17F SNP) with OA risk." (PMID 30658595, 2019). "The pathway “Role of IL-17A in arthritis pathway” was also enriched with –log (p-value) 1.64." (PMID 29731966, 2018). "Moreover, IL-17A was overexpressed (5-fold) before arthritis with a huge expression (55-fold) during the arthritis phase." (PMID 29472591, 2018). "Using WT and IL-17AKO mice we explored whether IL-17A is critically involved in the development of both arthritis and arthritis-evoked pain." (PMID 28871176, 2017). "WJHL can relieve the arthritis by inhibiting Th17 activation and decreasing IL-17A secretion." (PMID 28562338, 2017). "Supporting the anti-inflammatory role of PRL in arthritis, PRL-receptor-null mice exhibited increased joint swelling and higher joint expression of the genes encoding for TNFα, IL-1β, IL-6, IFNγ, IL-17A, IL-21, IL-22, IL-23, and IL-10 when subjected to monoarticular AIA (MAIA)." (PMID 28506283, 2017). "Knocking out IL-17A or treatment with anti IL-17 antibodies or blocking IL-17 receptor may alleviate arthritis." (PMID 29312540, 2017). "Thus the beneficial clinical effect of IL-17A neutralisation in some forms of arthritis is likely to result not only from the interference with the inflammatory process but also from the interference with processes of nociception." (PMID 28871176, 2017). "The role of Th17 cells in arthritis is likely to expand beyond its prototypic cytokine IL-17A." (PMID 29142301, 2017). "Furthermore, treatment with neutralizing anti-IL-17A slightly inhibited the progression of arthritis in SKG mice." (PMID 26903711, 2016). "Nevertheless, data provides a rationale for designing potential therapies that may utilize IL-17A blockade in combination with conventional treatment regimen for patients with metastatic BC that also present with arthritis." (PMID 24674692, 2014). "Indeed in our previous publications, we have shown that BC-associated metastasis is significantly augmented in mice with arthritis and that IL-17A, IL-6, COX-2, VEGF, MMP-9, IGF-II, M-CSF and TNF-α are all major players." (PMID 24674692, 2014). "In this model, arthritis is suppressed in the absence of IL-17A, suggesting that the pathogenic T cells are indeed Th17+ cells." (PMID 22229105, 2012). "Neutralizing IL-17A has an ameliorating effect on the severe arthritis observed in CCR2−/− mice." (PMID 21991368, 2011). "Indeed, the expression levels of IL-17A were found to be significantly increased in the joints of Tg mice, which correlated with severe arthritis." (PMID 22192790, 2011). "Since our collagen-induced arthritis model is different from the Il1rn-dependent model in which polyarthritis develops spontaneously, it is difficult to compare directly which therapeutic method, anti-IL-17A or anti-CXCR2 is more effective." (PMID 21991368, 2011). "The present observation that IL-23 regulates IL-17A production in both Th17 cells and TCRγδ T cells in experimental arthritis underscores the need for further studies to unravel the potential of IL-23 as a therapeutic target in the pathogenesis of human destructive arthritis." (PMID 20017902, 2009). "This study is representative of the roles of IL-17A and IL-10 polymorphisms, mainly in the oligoarthritis and polyarthritis types of JIA (which are the two major groups) in a Finnish population, as the numbers of ERA patients and other types of arthritis were low." (PMID 39125893, 2024). "Experimental arthritis models suggest that IL-17A-producing cells may play a more critical role in the erosive stages of RA rather than early disease onset, indicating potential benefits of IL-17A blockade in specific subsets of RA patients." (PMID 39507540, 2024).